INS (insulin)
Diseases named in the same sentence as INS in open-access papers (continued):
Sharing a sentence is not in itself a finding about the gene and the disease.
diabetes (continued). "Finally, sulfatide might be a good addition to injectable commercial insulin formulations, because it strongly inhibits fibroblast growth, thus potentially reducing adverse fibroblast growth and improve well-being in patients with diabetes." (PMID 39290144, 2024). "Background and Objectives: Type 1 diabetes mellitus (T1DM) is a chronic and serious condition that is characterized by inadequate pancreatic-β-cells’ insulin production." (PMID 38256380, 2024). "In type 1 diabetes mellitus (T1DM), treatment protocol and disease management aim to monitor blood glucose, insulin administration via multiple injections or insulin pumps, diet, and physical activity." (PMID 38255417, 2024). "Furthermore, given that the ketogenic diet may influence insulin sensitivity and fat metabolism differently among individuals, personalized ketogenic dietary approaches could emerge as a significant research direction in diabetes management." (PMID 39483785, 2024). "The stimulatory effect of insulin on AVP secretion was confirmed in several other species and in patients with type 1 diabetes mellitus." (PMID 39769071, 2024). "Hits in this list included widely used diabetes drugs, such as sulfonylureas, PPAR receptor agonists, and insulin sensitizers." (PMID 39386475, 2024). "In type 2 diabetes mellitus (T2DM) patients, in addition to impaired insulin secretion and impaired insulin-induced glucose uptake, enhanced endogenous glucose production (EGP) is known to contribute to the development of hyperglycemia." (PMID 38604598, 2024). "Obarorakpor and colleagues also targeted IAg7/insulin B9-23, and protected NOD.CD28-/- mice which develop accelerated diabetes." (PMID 39351219, 2024). "The possibility of treating diabetes, in an induced diabetic rat model, by SeEx-C NPs was examined by monitoring FBG and insulin levels." (PMID 38461158, 2024). "Mechanistically, chitosan’s hyperglycemic actions against diabetes mellitus are induced by PI3K/Akt signaling pathway that controls pancreatic β-cell activity, insulin secretion, and glucose metabolism." (PMID 38786486, 2024). "Identifying either T2D patients, irrespective of BMI, or obese patients, without diabetes, who are at imminent risk of a fragility fracture is rather difficult because of the dearth in knowledge about how the interactions among diet, obesity, and insulin insensitivity affect bone." (PMID 39012489, 2024). "For type 1 diabetes mellitus (T1DM), to keep their blood glucose levels within a target range and avoid problems, patients must take insulin therapy for the rest of their lives and exercise cautiously." (PMID 39658013, 2024). "The frequency of diabetes medication use like sulfonylurea (p < 0.001), GLP-1r (p = 0.007), SGLT2i (p < 0.001), DDP4 (p < 0.01), and insulin (p < 0.001) also showed significant differences between clusters." (PMID 38472402, 2024). "Patients with SVD were older, comprised more women, and had a longer duration of diabetes, higher SBP, and greater use of insulin and ACEIs." (PMID 39829954, 2024). "Section Diabetes mellitus biomarkers discuss DM biomarkers that have a strong relationship with diabetes, such as glucose, HbA1c, GHSA, and insulin, as well as novel biomarker." (PMID 39091901, 2024). "However, insulin therapy could influence the development of other diabetes complications." (PMID 39295783, 2024). "Interestingly, large epidemiological evidence suggests that Type 2 Diabetes Mellitus (T2DM) is strongly associated with cognitive impairment and dementia due to failure in the action of glucose handling in the neurons as a consequence of impaired brain insulin signaling." (PMID 38287296, 2024). "To examine the impact of diabetes on the MHb and IPN, we used an STZ model to induce a state of insulin depletion and chronic hyperglycemia, resulting in elevated blood glucose and elevated HbA1C at 6- and 12-week endpoints." (PMID 39763617, 2024).
diabetes (continued). "Sixthly, the protocol for STZ-induced diabetes mostly induces a mice form of type 1 diabetes, while GDM is more likely to type 2 diabetes, characterized by elevated levels of insulin, which has certain limitations in explaining the mechanism of GDM." (PMID 38375483, 2024). "Previously, in the context of diabetes, SIRT6 in pancreatic β‐cells has been shown to regulate insulin secretion in response to glucose stimulation, reducing cellular dysfunction and apoptosis." (PMID 38967361, 2024). "Interestingly, this study also found higher rates of cancer with a longer duration of diabetes and also among insulin users, pointing out that poor-controlled hyperglycemia requiring insulin use might be a culprit for increased cancer risk, a finding that is also suggested by our current study." (PMID 39050345, 2024). "This study has highlighted that individuals with type 2 diabetes using daily insulin prefer rtCGM over traditional SMBG due to perceived health benefits, the facilitation of increased engagement with diabetes-related care, and the general acceptability of use." (PMID 38932793, 2024). "Type 1 diabetes mellitus (T1DM) is an autoimmune disease, and it is characterized by the destruction of the insulin-producing pancreatic β-cells, mediated by T-lymphocytes." (PMID 39768947, 2024). "The use of this technology aids diabetes self‐management and has been shown to improve glycaemic metrics for patients using both multiple daily injections (MDI) of insulin and insulin pumps." (PMID 38268307, 2024). "Conversely, diabetes mellitus (DM), particularly type 2 diabetes (T2D), is a long-term metabolic illness characterized by hyperglycemia brought on by insulin resistance or insufficient insulin secretion." (PMID 39139325, 2024). "Currently, there are various induction methods for animal models of diabetes, with the chemical agent STZ being a common method used to disrupt the pancreatic β cells in experimental animals, leading to a decrease in insulin secretion." (PMID 39728311, 2024). "Type 2 diabetes mellitus (T2DM) is one of the most common chronic diseases, characterized by insulin resistance and insufficient insulin production by the beta-cells of the pancreas that result in elevated blood glucose levels." (PMID 39310638, 2024). "Other types include type 1 diabetes mellitus (T1DM), which is the result of autoimmune death of insulin‐producing β‐cells, and gestational diabetes (GD), which occurs during pregnancy due to hormonal change." (PMID 38726403, 2024). "When tested in zebrafish, ILP-Ap04, like human insulin, significantly lowers blood glucose in the STZ and glucose-induced model of diabetes." (PMID 38535452, 2024). "Currently, insulin therapy is effective but costly, and IDF data show that there are about 450 million people with diabetes worldwide, and the annual treatment cost is as high as USD 670 billion." (PMID 39272484, 2024). "Type 2 diabetes mellitus (T2DM) is a multifactorial metabolic disorder characterized by chronic hyperglycemia resulting from impaired insulin activity and insulin secretion." (PMID 39198298, 2024). "We prospectively recruited controls and patients with type 2 diabetes mellitus (T2DM), subjected them to the SITT, and calculated the K indices of the intravenous insulin tolerance test (KITT(iv)) and the subcutaneous insulin tolerance test (KITT(sc))." (PMID 38905235, 2024). "Turmeric's bioactive ingredient curcumin has attracted attention as a possible treatment for type 2 diabetic mellitus (T2DM), mainly because of its insulin-sensitizing, anti-inflammatory, and antioxidant qualities." (PMID 39759349, 2024). "Low‐dose insulin therapy suppresses MAPK signaling and ameliorates peripheral sensory nerve dysfunction in rats with STZ‐induced diabetes." (PMID 37795833, 2024). "Suppression of miR-23a upregulated insulin level and downregulated glucagon level in STZ-induced diabetes mice models, effectively promoting α-to-β like cell transition." (PMID 38517864, 2024).
diabetes (continued). "HbA1c levels were higher in the STAMPEDE and DSS studies than in the UCLA cohort, but insulin usage was much higher in the UCLA patients, suggesting more aggressive diabetes control in the modern era." (PMID 38911638, 2024). "The mean levels of the duration of diabetes (DDM), SBP, 2hPP, HbA1c, Cr, and microalbuminuria and insulin use were significantly higher in patients who developed retinopathy, during the 10-year follow up." (PMID 39574949, 2024). "Three studies, all with high risk of bias, assessed insulin administration as an outcome using various measures—diabetes social support interview (DSSI); scores for adherence to the medication regimen; and insulin dose adjustment behavior." (PMID 40302946, 2024). "During their hospitalization, 43% of patients with diabetes received metformin, 22.7% received a DPP4 inhibitor, 18.8% received a sulfonylurea, 18.1% received insulin, 1.9% received an SGLT2 inhibitor and 0.1% received a GLP1 receptor agonist." (PMID 39208154, 2024). "We utilized a combination of Medical Subject Headings (MeSH) terms and keywords such as "Type 2 Diabetes Mellitus", "SGLT2 inhibitors", "DPP-4 inhibitors", "Metformin", "Insulin", and "combination therapy"." (PMID 39723311, 2024). "These questionnaires include Insulin Treatment Appraisal Scale (ITAS), Problem Areas in Diabetes (PAID), Type-2 Diabetes Stigma Assessment Scale (DSAS-2), Diabetes Obstacles Questionnaire (DOQ)." (PMID 39453515, 2024). "The overexpressing of CTRP9 using adenovirus vectors has been shown to effectively reduce blood glucose and insulin levels in ob/ob mice, suggesting a protective effect of CTRP9 against diabetes." (PMID 39575169, 2024). "Of the 37 pathways associated with downregulated genes, the most relevant pathways to β-cell biology and/or diabetes included MAPK signaling, apoptosis, TNF signaling, NFKβ signaling, insulin resistance, and pancreatic cancer." (PMID 39022651, 2024). "Previous studies have reported several features of CPI-DM: rapid onset of severe hyperglycemia, the presence of diabetic ketoacidosis or an extreme reduction in C-peptide levels, and continuous insulin dependence for glycemic control following the development of diabetes." (PMID 39722806, 2024). "In terms of diabetes, after TAC treatment, the fasting blood glucose and serum insulin of diabetic model rats were significantly reduced, consistent with previous research results." (PMID 39687865, 2024). "The improvements observed in this study on glycemic indices and lipid profile of patients with diabetes were consistent with those observed in previous studies (in decreasing FBS, insulin, increasing HDL and reduction of LDL and total cholesterol." (PMID 38778308, 2024). "Age, sex, smoking, BMI, LVEF, diabetes, hypertension, obesity, fasting glucose, fasting insulin, the HOMA-IR index, hs-CRP, statin use and insulin use were included in the multivariate analysis." (PMID 39590197, 2024). "Diabetes mellitus (DM) is a complicated multisystemic metabolic disease featured by hyperglycemia, resulting from an insufficiency of insulin secretion or insulin resistance, which renders the body unable to respond fully to insulin." (PMID 38671903, 2024). "In conclusion, we demonstrate that heterozygous LDL receptor deficient hamsters developed spontaneously sever HTG on normal chow diet when diabetes is induced by STZ and both hyperglycemia and HTG in diabetic hamsters are insulin dependent." (PMID 39529532, 2024). "Type 2 diabetes mellitus (T2DM), often referred to simply as diabetes, encompasses a diverse group of diseases characterized by hyperglycemia resulting from defects in insulin production, insulin action, or both." (PMID 39518562, 2024). "Type 2 diabetes mellitus (T2DM) is primarily characterized by reduced insulin sensitivity (insulin resistance) and impaired insulin secretion." (PMID 39407609, 2024).
diabetes (continued). "Type 2 diabetes mellitus (T2DM) is a chronic metabolic disorder that leads to elevated blood glucose levels, primarily due to the body’s inefficiency in using insulin." (PMID 39335472, 2024). "Therefore, the objective of this study is to establish a diabetes model in rats using alloxan, known for destroying beta cells by chemical compounds, to evaluate the dose of alloxan, the induction rate of DM, and the stability of blood glucose with insulin treatment." (PMID 39070316, 2024). "In diabetes, 20-HETE induces insulin secretion and protects pancreatic islet cells from apoptosis by activating the free fatty acid receptor 1 (FFAR1/GPR40)." (PMID 39959811, 2024). "Persons with type 1 diabetes mellitus (T1DM) are advised to count carbohydrate intake, adjust bolus insulin delivery to food intake, and consume an overall healthy, high-quality diet." (PMID 38638557, 2024). "Additionally, these overexpression models can be applied to further explore ANXA1’s potential as a therapeutic target for diabetes, and to determine whether β cells exposed to glucotoxicity can maintain sufficient insulin production in the presence of elevated ANXA1 levels." (PMID 39432712, 2024). "Polysaccharides, found abundantly in edible plants, hold promise for managing diabetes by reducing blood glucose levels (BGL) and insulin resistance." (PMID 38931372, 2024). "We tested the postprandial glucose, insulin, and GLP-1 response to a high-protein, low-fat diabetes-specific nutritional shake (DSNS-HP) compared to isocaloric instant oatmeal (IOM) in a randomized, controlled, crossover study in adults with T2DM (n = 24)." (PMID 38903056, 2024). "Subjects using OAD alone (50.7 ± 9.2 years old) are older in diabetes onset compared to those under therapy of both OAD and insulin (48.0 ± 9.4 years old) (P = 0.021)." (PMID 38263010, 2024). "This idea is supported by the results of studies focusing on the role of NLGN2 in insulin secretion and on the potential of NLGN2 mimetics as tools for treating patients with diabetes." (PMID 38413734, 2024). "In view of the reduced diabetes incidence in the recipients of NOD.HET and NOD.KO cells, islet infiltration by H/E and β-cell area as reflected by insulin staining were assessed." (PMID 39359722, 2024). "Type 2 diabetes mellitus (T2DM) is characterized by insulin resistance, impaired insulin secretion, and beta cell dysfunction, often leading to chronic hyperglycemia and associated complications." (PMID 39350820, 2024). "A deficiency in SLC39A5 weakens glucose sensitivity and reduces insulin secretion, indicating that SLC39A5 has potential as a therapeutic target for diabetes-related metabolic diseases." (PMID 39850557, 2024). "Are there alternatives to insulin therapy in 6q24-related transient neonatal diabetes (6q24-TND); and does thiamine supplementation improve glycemia in SLC19A2-diabetes also known as Thiamine-Responsive Megaloblastic Anemia (TRMA) syndrome?" (PMID 39025920, 2024). "Furthermore, rodent models of diabetes show altered neuromodulation systems operated by adenosine, ATP, or endocannabinoids, which control synaptic activity and brain energy metabolism, and might interact with brain insulin signaling." (PMID 37794263, 2024). "For people with diabetes, controlling blood glucose level (BGL) is a significant issue since the disease affects how the body metabolizes food, which makes careful insulin regulation necessary." (PMID 39686207, 2024). "Diabetes mellitus (DM) is a condition that affects the body's metabolism and causes hyperglycemia due to a lack of insulin production or resistance to insulin." (PMID 38646241, 2024). "Among diabetes medications, there were significant difference in the prescription of biguanides, sodium-glucose cotransporter 2 (SGLT2) inhibitors, and insulin." (PMID 38243047, 2024). "EAs are less likely to use diabetes management technologies such as continuous blood glucose monitors (CGM) and insulin infusion pumps." (PMID 39110496, 2024).
diabetes (continued). "Insulin resistance, a key factor in the development of type 2 diabetes mellitus (T2DM), is defined as a defect in insulin-mediated control of glucose metabolism in tissues such as liver, fat and muscle." (PMID 39749015, 2024). "In 2019 the FDA authorised the first interoperable insulin pump, also known as an alternate controller-enabled (ACE) insulin pump, which would allow PLWD to customise treatment through their diabetes management devices." (PMID 38041737, 2024). "In adults with type 1 diabetes mellitus, Sotagliflozin, an SGLT-2 inhibitor, when used as an adjunct to insulin therapy, significantly reduced the predicted 5- and 10-year cardiovascular disease risk, possibly by reducing body weight and blood pressure." (PMID 39861067, 2024). "Type 2 diabetes mellitus (T2DM) is a metabolic disorder characterised by hyperglycemia determined by insulin resistance and impaired insulin secretion." (PMID 38398421, 2024). "Diabetes induction with overfeeding and excessive glucose consumption is accompanied by higher expression of inflammatory cytokine genes in the pancreas and lower insulin production and GLU2 gene expression, which could be due to more β‐cell dysfunction in response to the inflammatory milieu." (PMID 38279951, 2024). "One of the important incretins in the improvement of diabetes is glucagon-like peptide (GLP-1), which is secreted by the gut and reduces the apoptosis of pancreatic β-cells and improves insulin sensitivity." (PMID 39796443, 2024). "Our systematic review demonstrated that Asian patients with BMI <30 kg/m2 can achieve significant diabetes remission, as well as improvements in HbA1c, FBG, 2hPG, and HOMA-IR, BMI, WC, fasting C-peptide, TC, TG, and the use of OHA/insulin." (PMID 39507886, 2024). "Type 2 diabetes mellitus (T2DM) is a common illness among the elderly and is coined as a metabolic disorder characterized by ineffective insulin secretion or defective insulin action, or both." (PMID 38651420, 2024). "MD education along with insulin therapy, as recommended by the guidelines, to individuals with T1DM will contribute to improving the prognosis of diabetes." (PMID 38724988, 2024). "In addition, NDOs can regulate insulin sensitivity, blood glucose, and lipid metabolism by influencing microorganisms to produce beneficial metabolites, such as SCFAs, amino acid metabolites, and bioactive polypeptides, thereby alleviating the onset and progression of diabetes." (PMID 38998662, 2024). "Diabetes mellitus (DM) is a metabolic condition defined by high blood glucose levels that can be caused by either a lack of or inability to utilize insulin." (PMID 38924022, 2024). "To identify the factors associated with adiponectin, we performed linear regression analyses in factors including age, sex, duration of diabetes, BMI, lipid profiles, FFA, HbA1c, FBG, fasting insulin, ALT, AST, antidiabetic therapy, and lipid-lowering therapy." (PMID 38886355, 2024). "As expected, the insulin therapy group had a higher prevalence of family history of diabetes, previous GDM, and macrosomia compared to the non-insulin therapy group." (PMID 39408152, 2024). "In addition, as osteocalcin is thought to influence the pathogenesis and progression of diabetes mellitus by regulating insulin secretion and sensitivity, future studies may aim to further explore the role of osteocalcin in the development of diabetes mellitus." (PMID 39872315, 2024). "Here we present a case of a 30-year-old male individual initially diagnosed with uncontrolled type 1 diabetes mellitus (T1DM) since the age of 15, and treatment with high insulin doses has been unsuccessful." (PMID 39108603, 2024). "Despite the various models of induced diabetes and the utilized animals, the evidence indicates OLE attenuated total body and fat-specific mass gain while glucose tolerance and insulin sensitivity were improved." (PMID 39590817, 2024).